SHBG (sex hormone binding globulin)
Diseases named in the same sentence as SHBG in open-access papers (continued):
Sharing a sentence is not in itself a finding about the gene and the disease.
Hirsutism (continued). "PCOS untreated had significantly higher hirsutism score, free testosterone, and free androgen index and lower SHBG and platelets." (PMID 35800349, 2022). "Another study used probiotic supplementation for 12 weeks in PCOS patients, resulting in significant improvements in hirsutism, total testosterone and SHBG values." (PMID 34350129, 2021). "They reported a significant decrease in fasting plasma glucose, serum insulin, HOMA-IR, TT, FAI, and hirsutism as well as a significant increase in SHBG and total antioxidant capacity in the group receiving 4000 IU of cholecalciferol daily." (PMID 29946756, 2019). "ZNT1 showed no statistical significant correlations with PCOS indicators, namely, testosterone, SHBG, or the Ferriman–Gallwey score of hirsutism." (PMID 28303117, 2017). "It must be kept in mind that in our study, total testosterone levels, FAI and hirsutism significantly decreased and significantly SHBG levels that was against two previous meta-analysis studies." (PMID 29186759, 2017). "Our findingssupport the findings from other studies that foundno correlation between leptin and SHBG levelsin women with hirsutism and subjects withPCOS." (PMID 25493169, 2012). "The keywords used were BS, sleeve gastrectomy, gastric bypass, gastric banding, menstrual irregularities, free testosterone, total testosterone, hirsutism, SHBG, lutenizing hormone, antimullarian hormone (AMH), follicle-stimulating hormone, and pre-term deliveries." (PMID 41561041, 2025). "Elevated SHBG reduced the pool of bioavailable androgens, thereby mitigating the hyperandrogenic drive, while reductions in circulating testosterone directly alleviated clinical manifestations such as hirsutism and acne in the CL22209-supplemented subjects." (PMID 41497317, 2025). "Furthermore, supplementation significantly reduced serum insulin, HOMA-IR, TT, FAI, and hirsutism and increased SHBG." (PMID 38994457, 2024). "Androgenicity outcomes were reported by up to 14 studies and included hirsutism, which was reported as the Ferriman-Gallwey (FG) or modified Ferriman-Gallwey, total and FT levels, sex hormone binding globulin (SHBG), dehydroepiandrosterone-sulphate (DHEAS), androstenedione and free androgen index." (PMID 38163998, 2024). "Other important parameters, including TT, FAI, SHBG, and hirsutism levels, were also investigated." (PMID 38994457, 2024). "However, the limited number of studies assessing SHBG and hirsutism requires careful interpretation of these findings, as the evidence is not yet conclusive." (PMID 39599701, 2024). "Therefore, lower SHBG levels would lead to higher levels of free androgens, which cause clinical symptoms of PCOS, such as hirsutism, alopecia, and acne." (PMID 36835989, 2023). "High-dose vitamin D supplementation resulted in significant reductions in total testosterone, free androgen index, hirsutism, and C-reactive protein levels, as well as a significant increase in SHBG and total antioxidant capacity when compared to the low-dose supplementation and placebo groups." (PMID 34063835, 2021). "On the other hand, in women who developed hirsutism at the sixth month of treatment, SHBG levels were found to be statistically significantly lower and DHEAS levels were found to be statistically significantly higher than at the beginning of the treatment (p < 0.05)." (PMID 34548957, 2021). "However, clinical features suggestive of PCOS, anovulation and clinical evidence of hirsutism, were documented in 25.8% and 11.2% of the female testosterone cohort, respectively, and in 26.9% and 12.1% of the female SHBG cohort, respectively." (PMID 30256433, 2019). "The measures collected from the participants included hirsutism (from facial scoring only), BMI and waist circumference, insulin and glucose levels, and hormone analysis to test total testosterone and sex hormone binding globulin (SHBG), which were used to calculate a free androgen index." (PMID 30463276, 2018).
Hirsutism (continued). "Moreover, probiotic supplementation for 12 weeks to women with PCOS led to a significant improvement in hirsutism, total testosterone and SHBG values." (PMID 30217229, 2018). "Further, high concentrations of insulin reduce circulating levels of sex hormone binding globulin (SHBG) and increase levels of free testosterone, and the latter leads to menstrual disturbance, development of ovarian cysts, hirsutism, and anovulatory infertility." (PMID 28274268, 2017). "The induction or increase of acne and hirsutism by androgenic progestins results from reduction of estradiol and sex hormone-binding globulin (SHBG) levels, leading to higher absolute and relative concentrations of endogenous androgens and unbound androgenic progestins." (PMID 26885361, 2016). "Hirsutism can be found in approximately 50% of patients with CS mainly attributed to adrenal androgen excess; endogenous hypercortisolism also correlates positively with free androgen levels probably due to SHBG reduction." (PMID 25580312, 2014). "In contrast, although there is a slight increase in SHBG with the use of estradiol and a mild antiandrogenic effect of dienogest, when compared to compositions with ethinylestradiol, the effect on signs of excess androgens such as hirsutism and androgenetic alopecia is smaller." (PMID 41415708, 2025). "Testosterone, SHBG, FAI, DHEAS, androstenedione, oestradiol and hirsutism by Ferriman‐Gallwey scores." (PMID 39996383, 2025). "Because of that, we conducted this meta-analysis in which we aimed to assess the effects of bariatric surgery on menstrual irregularities, free and total testosterone, hirsutism, AMH, sex, SHBG, LH, FSH, and pre-trem deliveries in women with PCOS." (PMID 41561041, 2025). "BS reduced menstrual irregularities, hirsutism, total and free testosterone, AMH, and LH and increased SHBG." (PMID 41561041, 2025). "Results from this RCT indicated improved subjective hirsutism after COCP treatment, as well as decreased testosterone and increased SHBG levels." (PMID 36939017, 2023). "SHBG levels were discerned to be lower and DHEAS levels were higher compared to those at the beginning of treatment in patients who developed hirsutism at the sixth month of the treatment (p < 0.05)." (PMID 34548957, 2021). "T, SHBG, and FAI were negatively correlated (−0.13, −0.10, and −0.11, respectively) (P < 0.05), while acne, hirsutism, fasting insulin, and HOMA-IR were positively correlated (0.079, 0.11, 0.084, and 0.082, respectively) (P < 0.05)." (PMID 34744814, 2021). "Acne, T, SHBG, FAI, hirsutism, fasting insulin, and HOMA-IR were significantly correlated with SAS-SS." (PMID 34744814, 2021). "Reduction in systolic blood pressure glucose, DHEAS, AS, hirsutism score, testosterone levels, FAI and LH levels and an increase in lipids and SHBG was indicated (p<0.05)." (PMID 33329391, 2020). "This dual metabolic–endocrine pathology manifests in metabolic abnormalities: it exacerbates ovarian androgen overproduction and reduces sex hormone-binding globulin (SHBG) synthesis, amplifying hyperandrogenic reproductive manifestations such as hirsutism, acne, and anovulation." (PMID 40941484, 2025). "Synbiotic supplementation showed improvement on sex hormone binding globulin, hirsutism scores, hs-CRP, and NO levels, but not the other inflammatory biomarkers in PCOS patients." (PMID 39479136, 2024). "in a sensitivity analysis, hirsutism and SHBG were no longer significant (p = 0.11 for both; not shown)." (PMID 37583655, 2023). "We found that melatonin consumption for 12 weeks in women with PCOS significantly decreased hirsutism and total testosterone levels yet did not influence SHBG values." (PMID 31139144, 2019). "Our results provided evidence that vitamin D and probiotic co-supplementation for 12 weeks in women with PCOS significantly improved hirsutism and total testosterone concentrations, but did not affect SHBG values." (PMID 30665436, 2019).
Hirsutism (continued). "Secondary outcomes include: the effect of the intervention on the PCOS phenotype, waist circumference, waist to hip ratio, ovulation rates, total testosterone, SHBG, free androgen index (FAI), AMH, hirsutism, acne, fasting glucose, blood pressure and all psychological parameters." (PMID 28264692, 2017). "Oner and muderris showed ω-3 also may be effective in decreasing hirsutism, BMI, LH, testosterone, insulin, Homeostatic model assessment (HOMA) levels, and increasing Sex hormone-binding globulin (SHBG) and TNF-α in women with PCOS." (PMID 25653669, 2015). "At the end of the study, there were significant decreases in BMI value, Ferriman-Gallwey hirsutism score, and serum total testosterone, free testosterone, and dehydroepiandrosterone sulfate (DHEAS) levels and a significant increase in sex hormone-binding globulin (SHBG) level in both groups." (PMID 39664998, 2024). "Additionally, in one small study, vitamin E with magnesium supplementation for 12 weeks was found to reduce hirsutism but not significantly alter testosterone or SHBG levels." (PMID 34063835, 2021). "Moreover, SHBG was the biochemical marker that best correlated with the following metabolic parameters: BMI (r = −0.531, p = 0.001), waist (r = −0.502, p = 0.001), HOMA-index (r = −0.468, p = 0.001), HbA1c (r = −0.300, p = 0.046), and hirsutism severity (r = −0.404, p = 0.001)." (PMID 33396396, 2020). "In multivariable analysis, SHBG remained an independent positive determinant of MG53, whereas hirsutism and follicle count were independent negative predictors." (PMID 41974999, 2026). "Although we observed slightly higher values of testosterone, SHBG, DHEAS and MDA levels in PCOS patients with hirsutism compared with PCOS cases without hirsutism, the differences were not statistically significant (p > 0.05)." (PMID 39336541, 2024). "But in all patients we found positive correlation between hirsutism score and FAI, cFT, cBT, as well as we found negative correlation between hirsutism score and SHBG." (PMID 25246891, 2012). "Considering all patients together we found positive correlations between hirsutism score and FAI, cFT, cBT as well as negative correlation with SHBG." (PMID 25246891, 2012). "Interestingly, in a recent study, the authors found a positive correlation between hirsutism score and FAI and a negative correlation with SHBG in both PCOS and NCAH patients." (PMID 39941345, 2025). "Overall, the co-administration of vitamin D and probiotic for 12 weeks to women with PCOS had beneficial effects on mental health parameters, serum total testosterone, hirsutism, hs-CRP, plasma TAC, GSH and MDA levels, but did not affect serum SHBG, plasma NO levels, acne and alopecia." (PMID 30665436, 2019). "We found that the co-administration of vitamin D and probiotic for 12 weeks to women with PCOS had beneficial effects on mental health parameters, serum total testosterone, hirsutism, hs-CRP, plasma TAC, GSH and MDA levels, but did not affect serum SHBG, plasma NO levels, acne and alopecia." (PMID 30665436, 2019).
hypogonadism (82 papers, 2010 to 2026). A disorder characterized by decreased function of the gonads. "Hypogonadism was causally associated with a higher risk of gout (effect size = 0.40, p < 0.03), while higher levels of SHBG was associated with a lower risk of chronic heart failure (effect size = − 0.09, p < .04)." (PMID 40316537, 2025). "In summary, the compound heterozygosity of SHBG variants identified in our patients describes preserved androgen-dependent functions and normal LH that argue against clinical hypogonadism." (PMID 41281936, 2025). "We discovered 157 significant genetic associations for total and free testosterone, SHBG, and hypogonadism." (PMID 40316537, 2025). "We identify associations with total testosterone, free testosterone, SHBG levels, and hypogonadism risk within European (EUR), African (AFR), admixed American (AMR), and East Asian (EAS) ancestry groups." (PMID 40316537, 2025). "Lower levels of total testosterone and SHBG were associated with a higher risk of hyperlipidemia, while hypogonadism was associated with a higher risk of hyperlipidemia." (PMID 40316537, 2025). "This study aimed to determine the relationship between mutations associated with impaired synthesis of the SHBG protein (rs727428, rs5934505, rs10822184) and hypogonadism in the Kazakh population of East Kazakhstan." (PMID 38107722, 2023). "The main reason suggested for AMT-related hypogonadism is that mitotane causes a rise in the hepatic SHBG synthesis and release which can lead to a reduction in cFT levels." (PMID 38269251, 2023). "Hypogonadism was found to be caused by the decrease in SHBG level and the associated total testosterone." (PMID 38107722, 2023). "Although longitudinal data would better clarify some aspects on the onset and progression of hypogonadism, our data highlight some interesting pathophysiological data underlying hypogonadism in this population, especially on the role of SHBG." (PMID 33289905, 2021). "Compensated hypogonadism was associated with higher SHBG levels and liver fibrosis scores, together with longer duration of HIV infection." (PMID 33515211, 2021). "In addition, we detected strong colocalization signals for PRMT6 and SHBG in the liver and adrenal gland that were linked to total testosterone and hypogonadism." (PMID 40316537, 2025). "Clinicians should recognize that SHBG genetic variants may cause aberrant biochemical findings that mimic hypogonadism, which should be included in the differential diagnosis when evaluating patients with unexplained hormonal abnormalities." (PMID 41281936, 2025). "Interestingly, SHBG has now been shown to be associated with symptoms of hypogonadism and mortality." (PMID 38132234, 2023). "Hypogonadism might be related to different pathophysiologic mechanisms, among which for the first time we found that liver fibrosis causing increase of SHBG was the primum movens of compensated forms of hypogonadism." (PMID 33515211, 2021). "The mean SHBG level was 61.93 nmol/L, only slightly greater than the 59.23 nmol/L observed in the hypogonadism group." (PMID 40647593, 2025). "Given the various roles of testosterone in men’s health, we conducted a multi-ancestral genetic analysis of total testosterone, free testosterone, SHBG, and hypogonadism in men within the Million Veteran Program (MVP)." (PMID 40316537, 2025). "Total testosterone, SHBG, and hypogonadism heritability estimates were 9–12%, 20–50%, and 5–9%, respectively." (PMID 40316537, 2025). "HIV-positive men are a suggested group for SHBG testing to assess possible biochemical hypogonadism." (PMID 40427034, 2025). "Few studies have analyzed ancestry-specific and trans-ancestry genes regulating total testosterone, free testosterone, SHBG, and hypogonadism in a diverse male cohort." (PMID 40316537, 2025). "The MVP provides a breadth of clinical and genomic data that has allowed us to conduct the most ancestrally diverse genetic analysis of testosterone, SHBG, and hypogonadism to date." (PMID 40316537, 2025).
hypogonadism (continued). "In the non-hypogonadism group, total testosterone and SHBG exhibited a strong positive correlation, while free testosterone and SHBG demonstrated a moderate negative correlation." (PMID 40647593, 2025). "Utilizing data from the MVP male cohort, we completed a large, multi-ancestral GWAS of total testosterone, free testosterone, SHBG levels, and hypogonadism." (PMID 40316537, 2025). "Hypogonadism in men is an important clinical state that warrants testing the SHBG levels, as biochemical hypogonadism is easy to miss in HIV-positive patients." (PMID 40427034, 2025). "In this study, we present a GWAS of total and free testosterone levels, SHBG levels, and hypogonadism in the Million Veteran Program (MVP), a large, multi-ethnic genetic biorepository from a hospital-based population." (PMID 40316537, 2025). "After the ancestry GWAS was completed, we conducted a meta-analysis to identify a consensus set of 188 associations affecting total testosterone, free testosterone, SHBG, and hypogonadism." (PMID 40316537, 2025). "In total, we discovered 24 genes with high probability (PP.H4 > 0.8) of shared causal variants between their expression and total testosterone levels, hypogonadism and SHBG levels." (PMID 40316537, 2025). "We observed a significant elevation of SHBG in patients with preoperative hypogonadism (22.6 vs. 27.4 nmol/L; p = 0.012)." (PMID 39337013, 2024). "Limitations of our study include the use of TT to diagnose hypogonadism which can underestimate the prevalence of hypogonadism due to the possible rise in serum SHBG in HIV patients." (PMID 38476640, 2024). "In men on hemodialysis vs. healthy men there were increased serum levels of SHBG (40.9 ± 26.9 vs. 27.6 ± 11.9 nmol/L; p = 0.031) and a significantly enhanced frequency of biochemical hypogonadism (22.2 vs. 3.9%; p = 0.011)." (PMID 39014506, 2024). "These medications induced secondary hypogonadism by lowering testosterone levels, and 7.7% of patients also had high SHBG levels." (PMID 38248773, 2024). "In univariate analyses, age, BMI, mCCI score, and hypogonadism were negatively correlated (p < .0001), while SHBG and FT were positively correlated with the IIEF 5 score." (PMID 37020191, 2023). "The highly significant reduction in SHBG recorded in the AZA model group indicated hypogonadism due to low testosterone and low sperm production." (PMID 37049533, 2023). "In this study LH, SHBG, TT and cFT variations as well as the prevalence and type of hypogonadism before and after AMT were evaluated in ten surgically treated ACC male patients under AMT." (PMID 38269251, 2023). "The levels of LH and FSH can help to distinguish between primary and secondary hypogonadism, while the levels of sex hormone binding globulin (SHBG) can identify altered levels of testosterone due to causes that alter the plasma levels of this protein." (PMID 35887806, 2022). "Such discrepancy in hypogonadism prevalence when using TT alone instead of complete hormonal profile results largely from the high SHBG values that characterize this population." (PMID 33289905, 2021). "Researchers believed that among men infected by HIV or HCV, TT measurement will underestimate the hypogonadism because of the “false increase” in TT induced by elevated SHBG." (PMID 34872528, 2021). "In conclusion, using a complete hormonal profile, including SHBG and cFT, we found a prevalence of 20.2% of true overt hypogonadism in HIV-infected males complaining about sexual symptoms." (PMID 33289905, 2021). "It is interesting to note that compared with T2DM, patients with LADA had higher SHBG level but lower rate of hypogonadism." (PMID 34135863, 2021). "Among them, we selected 94 patients with TT, SHBG, cFT, and luteinizing hormone (LH) available, and classified hypogonadism into overt (low TT and/or low cFT) and compensated (high LH, normal TT and cFT)." (PMID 33289905, 2021).